PRDM16 (PR/SET domain 16)
Description:
Transcription regulator that acts both as a histone methyltransferase or chromatin adapter, depending on the context. In the cytoplasm, acts as a histone methyltransferase, which catalyzes monomethylation of 'Lys-9' of free histone H3 (H3K9me1) during translation (By similarity). Monomethylated histone H3 is then transported to the nucleus and incorporated into nucleosomes where SUV39H methyltransferases (SUV39H1 and SUV39H2) use it as a substrate to catalyze histone H3 'Lys-9' trimethylation (H3K9me3) (By similarity). Probably one of the primary histone methyltransferases along with MECOM/PRDM3 that direct cytoplasmic H3K9me1 methylation (By similarity). In the nucleus, acts as a key chromatin adapter that mediates differentiation of brown and beige adipocytes, which are specialized in dissipating chemical energy in the form of heat in response to cold or excess feeding (By similarity). Following recruitment to chromatin by PPARG nuclear receptor, promotes differentiation of myoblastic precursors into brown adipose cells (By similarity). Mechanistically, acts by mediating recruitment of (1) EHMT1 histone methyltransferase, thereby inhibiting the expression of white adipose-selective genes or (2) mediator complex, activating genes that are highly expressed in brown adipocytes, such as UCP1, PPARA, and PPARGC1A (By similarity). Also mediates differentiation of beige adipocytes from white adipose cells following recruitment by PPARG (By similarity). In addition to adipocyte differentiation, also involved in tolerance to gut microbiota: following recruitment to chromatin by RORgammaT (RORC) in a subset of antigen-presenting cells, promotes differentiation of peripherally-induced regulatory T-cells (pTreg), which suppress inflammatory responses to commensal microorganisms (By similarity). Also required in adult heart to preserve mitochondrial function and inhibit hypertrophy with advanced age (By similarity). Functions as a repressor of TGF-beta signaling. [Isoform 4]: Binds DNA and functions as a transcriptional regulator. Functions as a repressor of TGF-beta signaling. May regulate granulocyte differentiation.
Synonyms: KIAA1675; MEL1; PFM13; MGC166915; KMT8F; CMD1LL; LVNC8
Tractability: PROTAC: ubiquitination databases record sites on it.
Target class: Enzyme; Transferase
Gene: Protein-coding gene on chromosome 1 (3,069,168 to 3,438,621, forward strand). Ensembl gene ENSG00000142611.
Subcellular location: Nucleus; Chromosome; Cytoplasm
Subcellular location (Human Protein Atlas): Nucleoplasm; Cytosol; Nuclear bodies
Pathways (Reactome):
Chromatin organization: PKMTs methylate histone lysines
Developmental Biology: Transcriptional regulation of brown and beige adipocyte differentiation by EBF2
Gene Ontology:
Molecular function: DNA-binding transcription factor binding; DNA-binding transcription repressor activity, RNA polymerase II-specific; protein binding; sequence-specific DNA binding; transcription cis-regulatory region binding; chromatin-protein adaptor activity; DNA-binding transcription activator activity, RNA polymerase II-specific; histone H3 methyltransferase activity; histone H3K9 methyltransferase activity; histone H3K9 monomethyltransferase activity; RNA polymerase II cis-regulatory region sequence-specific DNA binding; transcription coactivator activity; transcription coregulator activity; transcription corepressor activity; DNA-binding transcription factor activity
Biological process: negative regulation of DNA-templated transcription; negative regulation of transcription by RNA polymerase II; negative regulation of transforming growth factor beta receptor signaling pathway; positive regulation of DNA-templated transcription; protein maturation; beige fat cell differentiation; brown fat cell differentiation; heterochromatin organization; negative regulation of muscle cell differentiation; negative regulation of white fat cell differentiation; positive regulation of cold-induced thermogenesis; protein localization to chromatin; regulation of cellular respiration; regulation of transcription by RNA polymerase II; regulatory T cell differentiation; tolerance induction in gut-associated lymphoid tissue; chromatin remodeling; positive regulation of transcription by RNA polymerase II
Cellular component: cytoplasm; cytosol; nuclear body; nucleoplasm; nucleus; chromatin; chromosome; transcription repressor complex
Genetic constraint (gnomAD): Loss-of-function variants: 21 observed, 99.41 expected, observed/expected ratio (o/e) 0.21, 90% interval 0.15 to 0.3. The upper end of that interval is the gene's LOEUF score, 0.3, which puts it in group 1 of 6, group 1 being the genes least tolerant of losing a copy. Missense variants: 1,571 observed, 1,751.5 expected, observed/expected ratio (o/e) 0.9, 90% interval 0.86 to 0.94. Synonymous variants: 775 observed, 768.05 expected, observed/expected ratio (o/e) 1.01, 90% interval 0.95 to 1.07.
Gene-disease validity (ClinGen):
ClinGen rates the evidence that PRDM16 causes each of these diseases.
dilated cardiomyopathy (autosomal dominant): Strong. Cardiomyopathy which is characterized by dilation and contractile dysfunction of the left and right ventricles.
Cancer hallmarks: escaping programmed cell death (promotes)
Homologues: Orthologues: chimpanzee PRDM16 (99% identical), macaque PRDM16 (98% identical), dog PRDM16 (89% identical), rat Prdm16 (88% identical), mouse Prdm16 (88% identical), pig PRDM16 (87% identical), guinea pig PRDM16 (87% identical), tropical clawed frog prdm16 (76% identical). Paralogues in human: MECOM (52% identical).
Diseases named in the same sentence as PRDM16 in open-access papers:
PRDM16 is named in the same sentence as 151 diseases in open-access papers, as found by Europe PMC text mining. Sharing a sentence is not in itself a finding about the gene and the disease. The quoted sentences say what the papers report.
Obesity (87 papers, 2014 to 2026). Accumulation of substantial excess body fat. "Single nucleotide polymorphisms of PRDM16 are associated with various human diseases, leading to increased risk of migraines, obesity, and metabolic syndromes, as well as effects on heart function." (PMID 39895629, 2025). "In this study, we explored a gene therapy approach to treat obesity in agouti mice using adeno-associated viruses (AAVs) carrying PRDM16, FoxP4, or Follistatin (FST) genes, which are known to promote the browning of white adipose tissue." (PMID 39596212, 2024). "The activity and expression of PRDM16 in adipose tissue are closely associated with adipocyte thermogenesis and resistance to obesity, as evidenced by these distinguished studies." (PMID 39351529, 2024). "Studies involving different polymorphisms of PRDM16 have also shown significant correlations between genetic variants of the gene and the development of obesity in humans." (PMID 37386647, 2023). "A Saudi population study showed that the PRDM16 polymorphism (RS2651899) is a risk factor for obesity and significantly affects blood lipids." (PMID 35462933, 2022). "Clinical and basic studies have shown that the expression of PRDM16 is associated with obesity and diabetes and that PRDM16 signaling participates in the treatment of the two diseases." (PMID 36193156, 2022). "We also assessed the development of obesity and associated pathology in female Adipo-PRDM16 KO; Mstn-/- mice." (PMID 33220490, 2021). "The transcriptional coregulatory protein PRDM16 is required for beige fat activation, which is associated with protection from obesity and improved insulin sensitivity." (PMID 33220490, 2021). "Among the 57 studies which reported cORs, PRDM16: rs2651899 conferred the strongest association with obesity (cOR = 44.60, 95% CI: 11.60–172.02, P = 0.0001)." (PMID 34131278, 2021). "In summary, AKG supplementation promotes beige adipogenesis and alleviates HFD‐induced obesity in middle‐aged mice, which is associated with enhanced DNA demethylation of the Prdm16 gene." (PMID 31691468, 2020). "In human, the PRDM16 polymorphisms are associated with obesity as the A allele is dominant in the obese group." (PMID 31312653, 2019). "We found that PRDM16 gene polymorphism (rs2651899) was associated with a significantly increased risk of obesity and a significant effect on blood lipids profile." (PMID 29890628, 2018). "In conclusion, we found that the PRDM16 polymorphism (rs2651899) is a risk factor for obesity and significantly influences plasma lipids in the Saudi population." (PMID 29890628, 2018). "Therefore, there is still more work to be done to target the PRDM16 protein in thermogenic AT in order to battle obesity and the metabolic diseases that are associated with obesity." (PMID 40278960, 2025). "Compared to β3 adrenergic receptor agonist and GLP-1 receptor agonist, PRDM16 protein could represent a novel and promising therapeutic approach for combating obesity and its associated metabolic disorders." (PMID 39351529, 2024). "This may affect thermogenesis by downregulating the expression of Pparγ, Prdm16, and Pgc1α, thereby reducing energy and heat production, which in turn contribute to obesity and diminished metabolism associated with menopause." (PMID 38397839, 2024). "Despite a lack of studies on the effect of miR-21 role on the expression of thermogenic targets in PCOS, the use of miR-21 mimics in obesity induced by high-fat diet was associated with upregulation in multiple genes involved in thermogenesis, including PRDM16, PGC-1α, UCP1, and CIDE-A." (PMID 38987854, 2024). "Hypermethylation of PRDM16 increases the risk of obesity and diabetes, suggesting that PRDM16 may be a very effective therapeutic target for obesity and diabetes." (PMID 35462933, 2022). "Furthermore, clinical and basic studies have shown that the expression of PRDM16 is associated with obesity and diabetes and that PRDM16 signaling participates in the treatment of the two diseases." (PMID 35462933, 2022).
Obesity (continued). "There are indications that the PRDM16 may be implicated in a molecular mechanism related to brown extra fat cells and preadipocytes, and as such, it may possibly be related to obesity." (PMID 35454329, 2022). "As well as being linked to cardiovascular disease, PRDM16 deficiency has also been associated with the development of fibrosis, which is linked to multiple age-associated chronic diseases and PRDM16 methylation has been linked to obesity." (PMID 35354948, 2022). "However, the increased OR of obesity with the mutated genotypes of this polymorphism (AA and AG) suggests that this polymorphism significantly reduces the expression of the PRDM16 gene, thus leading to a lower thermogenesis process and increased BMI." (PMID 29890628, 2018). "This includes genes previously linked to diabetes and obesity, for example PRDM16 (refs 29, 30)." (PMID 25502755, 2014). "Our study successfully verified that LGZG, a traditional Chinese medicine formula renowned for its beneficial effects in obesity and other metabolic diseases, could stimulate 3T3-L1 adipocytes browning, and the regulation of miR-27b/PRDM16 signaling pathway may be linked to this browning effect." (PMID 39206264, 2024). "The SREBP2-LDL receptor axis is already a well-established target for cholesterol-lowering therapeutics in cardiovascular disease, and PRDM16 is a very attractive target for obesity and T2D." (PMID 41226287, 2025). "According to numerous studies, a number of medications, such as resveratrol, rutaecarpine, acadesine (AICAR), metformin, rosiglitazone, and liraglupeptide, can reduce obesity and diabetes by altering the expression and function of PRDM16." (PMID 40278960, 2025). "All these compounds activate the β3-ARs pathway and increase the expression of thermogenic markers such as UCP1, PRDM16, and PGC1α, thereby limiting obesity." (PMID 41011119, 2025). "The amounts and stabilization of PRDM16 protein are critical in controlling the formation and function of thermogenic adipocytes and in combating obesity." (PMID 39351529, 2024). "This review summarizes the function and regulation of PRDM16 in adipose tissue and proposes the application of this transcription factor as a potential target for treating obesity and its related metabolic disorders." (PMID 39351529, 2024). "In summary, it is still a long way to combat obesity and its related metabolic disorders by targeting PRDM16 protein in thermogenic adipose tissue." (PMID 39351529, 2024). "This review comprehensively examines various studies that focus on combating obesity by directly targeting PRDM16 in adipose tissue." (PMID 39351529, 2024). "PRDM16 not only directly regulates the formation and function of brown and beige fat but also indirectly modulates the expression of other genes to control obesity and its related metabolic diseases." (PMID 39351529, 2024). "Numerous studies have reported that various drugs can alleviate obesity and diabetes by modulating the expression and function of PRDM16." (PMID 39351529, 2024). "PRDM16 protein is short-lived and rapidly degraded, making the increase of its lifetime in adipose tissue a promising strategy for combating obesity." (PMID 39351529, 2024). "Taken together, Prdm16 mRNA expression is regulated by various microRNAs to facilitate the expression of brown-selective genes and resist obesity." (PMID 39351529, 2024). "Sinapic acid exhibited anti-obesity effects in multiple cell studies by downregulating Pparg, C/ebpa, Srebp-1c, and Fas and upregulating Ucp1, Pgc1a, and Prdm16." (PMID 36839173, 2023). "Induction of browning in iWAT by transgenic expression of PR domain-containing 16 (Prdm16) increases Ucp1 mRNA level and protects the mice from diet-induced obesity." (PMID 37465124, 2023). "It is of concern that some drugs for obesity or diabetes affect brown fat and thermogenesis, possibly through the activation of the PRDM16 signaling pathway." (PMID 35462933, 2022).
Obesity (continued). "A study showed that Hlx gene expression at the physiological level drives a complete thermogenesis process through PRDM16 coactivation and converts white fat to brown-like fat, thereby improving glucose homeostasis and preventing obesity and hepatic steatosis." (PMID 35462933, 2022). "In this review, we summarized the role of PRDM16 in adipose tissue and proposed the use of PRDM16 as a potential target for the treatment of obesity and diabetes." (PMID 35462933, 2022). "In conclusion, PRDM16 plays an important role in adipocyte transformation and thermogenesis, which are closely related to the occurrence of obesity and diabetes." (PMID 35462933, 2022). "PRDM16-related signaling pathways are involved in the pathogenesis of obesity and diabetes, and intervening in PRDM16 expression or affecting the function of PRDM16 is likely to be an effective strategy to treat these diseases." (PMID 35462933, 2022). "Conversely, mice with transgenic overexpression of PRDM16 in adipose tissue have increased beige fat activation and are protected from obesity and metabolic dysfunction." (PMID 33220490, 2021). "Mice with an adipocyte-specific knockout of PRDM16 have an ablation of beige fat function and develop obesity, insulin resistance, hepatic steatosis, and increased adipose tissue inflammation." (PMID 33220490, 2021). "PRDM16 is essential for the browning of adipose tissue; reduced expression of its protein promotes obesity with high-fat diet and increases visceral fat." (PMID 34579086, 2021). "Surprisingly, Adipo-PRDM16 KO; Mstn-/- and Mstn-/- were equally (Tukey post-hoc p = 0.15) and dramatically protected from obesity compared to Adipo-PRDM16 KO and WT control mice (Tukey post-hoc p < 0.001)." (PMID 33220490, 2021). "As in males, female Adipo-PRDM16 KO; Mstn-/- and Mstn-/- had comparable body weight (Tukey post-hoc p = 0.10) and were equally protected from obesity compared to Adipo-PRDM16 KO and WT controls (Tukey post-hoc p < 0.001)." (PMID 33220490, 2021). "Mice with beige fat-specific overexpression of Prdm16 driven by the aP2 promoter were protected from diet-induced obesity compared to littermate control mice." (PMID 32849287, 2020). "It has been reported that the raise of SIRT-1-mediated PPARγ deacetylation further facilitated the interaction of PPARγ and PRDM16, which eventually promoted brown features in white adipocytes to prevent obesity." (PMID 33551999, 2020). "Supportively, ablation of Prdm16 in fat impaired browning and led to obesity and insulin resistance." (PMID 28677104, 2018). "The current study assessed the association of PRDM16 gene polymorphism (rs2651899) and PDE4D gene polymorphism (rs295978) with obesity and blood lipids profiles in the Saudi population." (PMID 29890628, 2018). "Mice with knock-down of Prdm16 develop obesity, insulin resistance, and increased levels of subcutaneous adipose tissues." (PMID 28934139, 2017). "It is these effects that cause obesity-induced thermogenesis: in BAT and inguinal WAT, β3AR signaling induces PRDM16 and PGC1α via the β3AR–cAMP–PKA pathway and increases UCP1 expression in mice; PPARα and PPARγ are also involved in heat production through this signaling pathway." (PMID 39796158, 2024). "Consequently, PRDM16 has been identified as a potential therapeutic target for obesity and its related metabolic disorders." (PMID 39351529, 2024). "In contrast, the specific deficiency of PRDM16, a transcriptional regulator that promotes the differentiation of both brown and beige adipocytes, in brown adipocytes alone did not result in obesity." (PMID 38544573, 2024).